CDK6 (cyclin dependent kinase 6)
Diseases named in the same sentence as CDK6 in open-access papers (continued):
Sharing a sentence is not in itself a finding about the gene and the disease.
leukemia (77 papers, 2011 to 2026). A malignant (clonal) hematologic disorder, involving hematopoietic stem cells and characterized by the presence of primitive or atypical myeloid or lymphoid cells in the bone marrow and the blood. "Our data extend these findings in FLT3–TKD-mutated cells; we now demonstrate that CDK6 inhibition is also capable of inducing leukemia cell death in this setting." (PMID 30544932, 2018). "Notably, MECOM-r cases associated with CDK6 showed fusion junctions in intron 2 or 3 of CDK6, suggesting these leukemias are utilizing alternative enhancers within the CDK6 locus other than CDK6-AS1." (PMID 41057686, 2025). "CDK6 was also found to be positively associated with genes identified to contribute to the development of leukemia, including CCND2, DNMT3B, SOX4, and IKZF2, as well as being negatively associated with anticancer microRNAs, including miR-187, miR-9, miR-582, miR708, and miR-362." (PMID 33597968, 2020). "The cyclin-dependent kinase CDK6 is crucial gene associated with leukemia stem cells (LSCs)." (PMID 30555164, 2019). "B1 showed nanomolar cytotoxicity (IC50 = 0.04 μM) against MV4-11 leukemia cells by inducing G0/G1 arrest (via cyclin D1/CDK6 downregulation) and apoptosis." (PMID 41745466, 2026). "To further evaluate the impact of the truncated Cdk6 on leukemia progression, we injected our different cell lines intravenously into NSG mice." (PMID 39898030, 2025). "It remains to be determined how and to which extent CDK6 inhibition alters metabolism of cancer cells and which role CDK6 specifically plays in this context in BCR::ABL1+ leukemia." (PMID 39966356, 2025). "We analyzed the impact of CDK6’s C-terminus on its functions in a leukemia model, revealing a central role in promoting proliferation." (PMID 39898030, 2025). "IGF2BP3 targets mRNAs encoding important factors in leukemia, like MYC, CDK6, HOXA genes, and EPOR, causing their stabilization and overexpression in leukemia cells." (PMID 40389480, 2025). "The expression of c-Myb (a DNA-binding transcription factor) leads to the growth of leukemia by cyclin D3, CDK6, and Bcl-2." (PMID 39598723, 2024). "In order to study these factors, Rao's group created a library of compounds intended for the degradation of CDK6 for the treatment of various hematological diseases, including leukemia." (PMID 38845697, 2024). "CDK6 serves as a key regulator of hematopoietic and leukemia stem cell activation, important for the survival of T-ALL cells." (PMID 37767202, 2023). "employed the SCENIC network to delineate a subset of cells characterized by activation of CDK6 and E2F3, subsequently categorizing them as leukemia cells associated with cell cycle initiation." (PMID 38022588, 2023). "Functional enrichment analysis further revealed that a fair number of these circSPI1-related genes, such as IRF8, ICAM1, HOXA9, and CDK6, have mainly been involved in leukemic transformation and leukemia cells maintenance." (PMID 37124518, 2023). "In particular, viability of myeloma, leukemia and neuroblastoma cells was strongly dependent on CDK6 (median scores, −1.02, −0.90 and −0.78)." (PMID 37359725, 2023). "CDK6 regulates exit from quiescence and is required for normal function in hematopoietic stem cells and maintains self-renewal in leukemia stem cells." (PMID 35633393, 2022). "When HPCLSK BCR/ABLp210+ Cdk6−/− cells were transplanted, loss of CDK6 was associated with a reduced incidence of leukemia, mimicking the effects of published primary BM transplantation assays." (PMID 35406494, 2022). "Hyperactive CDK4 has been reported in epithelial malignancies in the endocrine tissues and mucosa while CDK6 activation was reported in certain mesenchymal tumors such as sarcomas and leukemias [reviewed in 1]." (PMID 36051751, 2022). "For example, CDK6 is an indispensable downstream effector in MLL‐rearranged AML, and knockdown of CDK6 reduces the self‐renewal LSC in MLL arrangements‐transformed mouse leukaemia." (PMID 33599085, 2021).
leukemia (continued). "One compound termed PROTAC YX-2-107, which degrades CDK6 by recruiting the Cereblon ubiquitin ligase, markedly suppressed leukemia burden in mice injected with de novo or TKI-resistant Ph+ ALL." (PMID 34573335, 2021). "In support for the importance of CDK6 activity in leukemia, an unbiased cDNA screen identified CDK6 as a gene promoting imatinib resistance in v-ABL transformed cells." (PMID 34573335, 2021). "Specific inhibition of CDK6 by palbociclib suppresses the self‐renewal ability of leukaemia‐initiating cells in MLL‐driven AML." (PMID 33599085, 2021). "Meanwhile, CDK6 overexpression and gene amplification have been reported in leukemias, lymphomas, and gliomas." (PMID 34361615, 2021). "Cyclin-dependent kinase 6 (CDK6), a regulatory enzyme of the cell cycle that plays an important role in leukemogenesis and the maintenance of leukemia stem cells (LSC), has the potential to predict the prognosis of AML." (PMID 33597968, 2020). "In vivo proof of concept for the leukemia-inhibitory and differentiation-inducing role of CDK6 inhibition was provided by a transplantation model of MLL-AF9+ AML with shRNA knockdown." (PMID 32260549, 2020). "Contrary to CDK4, the CDK6 gene is frequently amplified or overexpressed in a variety of human lymphomas and leukemias." (PMID 32260549, 2020). "The frequent overexpression of CDK6 in leukemia and lymphoma has put a focus on CDK6 dependent functions in the hematopoietic system." (PMID 33255177, 2020). "In Haferlach leukemia 2, Valk leukemia, and Stegmaier leukemia statistics, the CDK6 expression was significantly higher in AML patients than in normal samples, using the ONCOMINE database." (PMID 33597968, 2020). "Although murine leukemia cells (BCR-ABL1p185+) contain high levels of CDK6, CDK7, CDK8, CDK9, and CDK19, knockdown of CDK6, CDK7, CDK9, or CDK19 has little effect on cell survival and proliferation in an inducible system." (PMID 31628323, 2019). "We demonstrate that CDK6 has pRB-independent role in adipogenesis by regulating RUNX1, one of the downstream effectors of CDK610 known to be frequently mutated in human leukemia and play a role in hematopoiesis." (PMID 29523786, 2018). "Inhibition of CDK6 leads to remarkable anti-leukemia effect in T-ALL cell lines as well as mouse model." (PMID 30323192, 2018). "Western blot analysis showed that expression of CDK6 was very high in seven of nine of the leukemia cell lines investigated, the exceptions being THP-1 and U937 cells." (PMID 28286417, 2017). "CDK6 gene amplification and overexpression have been described in lymphomas, leukemias, squamous cell carcinoma, gliomas and medulloblastoma." (PMID 25625291, 2015). "Some CDKs can be considered oncogenic, e.g., CDK4 in familial melanoma, CDK6 in MLL-rearranged leukemia, and CDK8 in colon cancer." (PMID 25914884, 2015). "Consistently with their in vitro phenotype, Cdk6+/++Cdk6 cells gave rise to subcutaneous lymphoma-like tumors or leukemia with increased latency." (PMID 23948297, 2013). "MIR-124A has diverse regulatory functions: it is upregulated during chondrogenesis, is a potential silencer of CDK6 when downregulated in leukemia, and regulates NFκB." (PMID 24330828, 2013). "Analysis of publicly-available microarray data confirmed high-level expression of CDK6 in J.RT3-T3.5, relative to other leukemia cell lines (array probes mapped to the portion of CDK6 retained in the fusion)." (PMID 23637631, 2013). "Furthermore, CDK6 has been discovered to have essential roles in leukemic cells beyond its involvement in cell cycle progression, making it a notable target in leukemia." (PMID 41496019, 2026).
leukemia (continued). "Our data in leukemia suggest that long-term inhibition of CDK6 alone might reverse this phenotype, highlighting the need for further studies on long-term CDK6 inhibition in solid cancers." (PMID 39966356, 2025). "Notably, MECOM-r cases associated with CDK6 showed fusion junctions in intron 2 or 3 of CDK6, suggesting these leukemias are utilizing a different enhancer within the CDK6 locus." (PMID 39975890, 2025). "The transcriptional regulation of CDK6 and Bcl-2 (regulator proteins; block programmed cell death) influences the c-Myb transcription factor expression; thus, the CDK6 inhibitor may have an important influence on leukemia cells." (PMID 39598723, 2024). "Next, the researchers showed that knockdown of circSPI1 inhibited cell proliferation, induced partial myeloid differentiation, and enhanced apoptosis of leukemia cells through upregulation of the levels of expression of apoptosis-related proteins such as Bcl-2, CDK6, p-ERK1/2." (PMID 37124518, 2023). "Some studies have reported that CDK6 overexpression could affect lymphoma, leukemia, and other malignancies." (PMID 35571043, 2022). "The involvement of CDK6 in LSCs biology makes it an attractive target for leukemia therapy." (PMID 36033505, 2022). "Spearman correlation analyses between UHRF1 mRNA levels and the gene expression of MYC family members (MYC, MYCN, and MYCL1), as well as CDK4 and CDK6 in the Haferlach and Gu leukemia datasets, indicated positive associations between UHRF1 and c-Myc, CDK4, and CDK6 in ALL." (PMID 36077796, 2022). "Our results describe a new mechanism by which bort suppresses self‐renewal of LSC by NF‐ĸB‐dependent inhibition of CDK6 in MLL‐arranged leukaemia, indicating that bort might be a potential drug for AML patients with MLL rearrangements." (PMID 33599085, 2021). "While suppressing CDK6 expression alone exerts anti-leukemia effects in our pre-clinical studies in mice injected with primary Ph+ ALL cells, treatment with PROTAC YX-2-107 may not achieve a long-lasting therapeutic response." (PMID 34573335, 2021). "In the hematopoietic system, CDK6 regulates T cell development and promotes leukemia and lymphoma." (PMID 34248938, 2021). "Furthermore, the phenotypes resulting from HCK deficiency can be rescued by CDK6 overexpression, supporting that HCK maintains the self-renewal of leukaemia stem cells via CDK6 in AML." (PMID 34167558, 2021). "HCK maintains the self-renewal of leukaemia stem cells via CDK6 in AML and may be an ideal therapeutic target for eradicating LSCs without influencing normal haematopoiesis." (PMID 34167558, 2021). "Homologue-selective degraders for CDK6 have been developed and were able to significantly reduce leukemia burden in xeno-transplant experiments of Philadelphia chromosome-positive acute lymphoid leukemia with superior effects compared to CDK4/6 kinase inhibition." (PMID 33255177, 2020). "Previous studies have found that CDK6 is often overexpressed in both leukemia and lymphoma." (PMID 33597968, 2020). "Furthermore, Cdk6 was necessary for propagation of BCR-ABL-induced leukemia by the leukemic stem cells." (PMID 27323399, 2016). "CDK6 is highly expressed in human T-cell lymphoblastic lymphoma/leukemia (T-LBL/ALL)." (PMID 25914884, 2015). "Thus, it is plausible that the CDK6 rearrangement drives deregulated CDK6 expression and T-cell derived leukemia." (PMID 23637631, 2013). "The data were confirmed by using the Cdk6−/− mouse in a p185BCR-ABL leukemia model." (PMID 23948297, 2013). "Down-regulation of CDK6 results in significantly delayed leukemia formation." (PMID 21789792, 2011). "Altering CDK6 expression has major consequences for leukemia and lymphoma development." (PMID 21789792, 2011).
leukemia (continued). "That some MYB target genes (such as KIT, CDK6 and FLT3) exhibit a degree of correlation with MYB levels amongst the patient datasets probably reflects a wide range of driver mutations and a very heterogeneous genetic landscape amongst the complex karyotype leukaemias." (PMID 37996430, 2023). "Therefore, it is interesting to explore whether combined applications of bort, NF kB inhibitors, and CDK6 inhibitors contribute to the clinical intervention of MLL‐rearranged leukaemia." (PMID 33599085, 2021). "However, whether and how CDK6 is required for bort‐induced anti‐leukemogenesis effect in MLL‐rearranged leukaemia remains to be determined." (PMID 33599085, 2021). "Importantly, in our GWAS, which was also adjusted for white blood cell counts, we found association signals near genes involved in leukaemia and lymphoma development (CRK, BAK1, CDK6, MDFIC, BIK) as well as a significant enrichment of pathways related to immune cell proliferation." (PMID 33385171, 2021). "As expected, several previously reported genes with abnormal methylation in leukemias such as CPEB1, BLK, FLT3, ZCCHC7, EBF1, HDACs, IKZF1, RB1, CDK6, DOCK5, DPP10, MUC4, JAKs, KIT, KRAS, LINC01013, MAD1L1, NOTCH1, and STATs, among others, were also detected." (PMID 41226303, 2025). "Compared with normal B cells, high expression of cell proliferation markers such as Mki67, Cdk6, Cdkn2a and Hist1h1b, was noted in this cluster, indicating a BBC2 leukemia cell identity." (PMID 38730491, 2024). "I-BET 151 induced G1 phase cell-cycle arrest and apoptosis for mixed lineage leukemia (MLL), achieved by reducing the binding of BRD4 to the promoter regions of MYC, BCL2, and CDK6." (PMID 38539460, 2024). "Of note, our recent studies show that targeting CDK6 induces T-ALL apoptosis and inhibits the infiltration/metastasis of leukemia into different organs." (PMID 37108359, 2023). "A notable sub-class of PROTACs showed significantly better degradation of CDK6 over CDK4, suggesting a potential therapeutic use in certain leukemias such as in AML and Ph+ ALL." (PMID 36051751, 2022). "Recent studies have also shown that JAK-STAT signaling pathway genes and CDK6 are downstream targets of NUP98–KDM5A and that NUP98–KDM5A leukemia is vulnerable to JAK or CDK6 inhibition." (PMID 35805040, 2022). "On the other hand, we identified CDK6 and BCL2 as JQ1 targets for transcriptional silencing in SCLC cells, as in leukemia, lymphoma and neuroblastoma." (PMID 27764802, 2016). "For example, miR-495 functions as a tumor suppressor by targeting essential leukemia-related genes in MLL-rearranged leukemia and by down-regulating cyclin-dependent kinase 6 in glioblastoma multiforme cells." (PMID 25070379, 2014). "In a model of murine leukemia, c-JUN prevents the epigenetic silencing of the cell cycle kinase CDK6." (PMID 21789792, 2011). "Genetically knocking out or pharmacological inhibition of CDK6 can prevent activated Notch signaling from inducing leukemia, indicating that CDK6 serves as a downstream effector of Notch signaling." (PMID 37767202, 2023). "In addition, CDK6 is a direct target of MLL fusion proteins and plays an important role in the proliferation of MLL-rearranged leukemia." (PMID 34212178, 2021). "Among these differential expressions of genes, CDK6 was finally selected for further study because CDK6, a vital modifier of the cell cycle, is indispensable for the initiation and maintenance of MF9‐rearranged leukaemia." (PMID 33599085, 2021). "In agreement with this view, two studies showed that CDK6 but not CDK4 is required for the proliferation of MLL-rearranged leukemia, despite the fact that both kinases are expressed." (PMID 34573335, 2021). "Flavopiridol is an inhibitor of cyclin-dependent kinases (CDKs) (including CDK1, CDK2, CDK4, CDK5, CDK6, CDK7, CDK8, and CDK9) and has been investigated for the treatment of several types of cancers, including leukemia, liver cancer, and renal cancer, in clinical phase 2 trials (24, –, 26)." (PMID 31822599, 2019).
leukemia (continued). "Moreover, MLL-FPs are able to form a molecular complex with BRD4 (an epigenetic reader), PAFc and SEC to sustain the oncogenic expression of BCL2, CDK6, and MYC in MLL-r leukemias." (PMID 31157223, 2019). "These preclinical data suggest that CDK6 is a potential target for MLL-r leukemias; accordingly, there is an active phase Ib/IIa clinical trial out of the University of Ulm (NCT02310243) of palbociclib as monotherapy for adults with MLL-r leukemias." (PMID 28232907, 2017). "Because of the critical role played by CDK6 in MLL-rearranged AML and ALL, as well as in FLT3-ITD driven AML, CDK6 may be an effective therapeutic target in these leukemias." (PMID 25914884, 2015). "Also known as alvociclib, this wide spectrum CDK inhibitor targets CDK1, CDK2, CDK4, CDK6, CDK7 and CDK9 and displays antiproliferative efficacy in several solid tumours and sarcomas, as well as in leukaemia, lymphoma and multiple myeloma." (PMID 25625291, 2015). "In agreement with this hypothesis, several of the genes identified in our analysis have been suggested to be putative therapeutic targets in leukemia, with either preclinical or clinical trials underway (CDK4, CDK6, GSK3b, MYC, LCK, NFkB2, BCL2L1, NOTCH1)." (PMID 21356087, 2011). "Targeted inhibitors: Efforts to optimize CDK4/CDK6 blockade (e.g., combination regimens or PROTACs), PI3K/AKT/mTOR inhibition (rapalogues in trials), BH3 mimetics such as venetoclax, and menin inhibitors for KMT2A-rearranged leukemias, several of which have shown promising clinical activity." (PMID 41009342, 2025). "Due to growing evidence suggesting that CDK6 has several pro-tumorigenic functions besides the regulation of the G1-S transition, agents that reduce CDK6 expression are expected to suppress leukemia growth through canonical (kinase-dependent) and non-canonical (kinase-independent) mechanisms." (PMID 34573335, 2021). "MLL-r leukemias seem to be dependent on CDK6, but not on CDK4, for growth and proliferation." (PMID 28232907, 2017). "This dependence on CDK6 was not seen in non-MLL-r leukemias." (PMID 28232907, 2017). "CDK6, but not its close homolog CDK4, is frequently expressed at high levels in human and murine lymphoma and leukemia and has been proposed to be a driving force for these diseases." (PMID 23948297, 2013).